ISOC1 (isochorismatase domain containing 1)
Synonyms: CGI-111
Tractability: PROTAC: ubiquitination databases record sites on it; its protein half-life has been measured.
Gene: Protein-coding gene on chromosome 5 (129,094,711 to 129,114,031, forward strand). Ensembl gene ENSG00000066583.
Subcellular location (Human Protein Atlas): Endoplasmic reticulum; Vesicles
Gene Ontology:
Molecular function: protein binding
Cellular component: cytoplasm; peroxisome
Genetic constraint (gnomAD): Loss-of-function variants: 26 observed, 26.56 expected, observed/expected ratio (o/e) 0.98, 90% interval 0.72 to 1.36. The upper end of that interval is the gene's LOEUF score, 1.36, which puts it in group 5 of 6, group 1 being the genes least tolerant of losing a copy. Missense variants: 366 observed, 374.38 expected, observed/expected ratio (o/e) 0.98, 90% interval 0.9 to 1.07. Synonymous variants: 176 observed, 157.17 expected, observed/expected ratio (o/e) 1.12, 90% interval 0.99 to 1.27.
Homologues: Orthologues: chimpanzee ISOC1 (100% identical), macaque ISOC1 (99% identical), pig ISOC1 (97% identical), dog ISOC1 (97% identical), guinea pig ISOC1 (96% identical), mouse Isoc1 (95% identical), rat Isoc1 (95% identical), tropical clawed frog isoc1 (89% identical), zebrafish isoc1 (79% identical), rabbit ISOC1 (74% identical), Drosophila melanogaster CG11333 (28% identical), Drosophila melanogaster CG3663 (28% identical). Paralogues in human: ISOC2 (34% identical).
Diseases named in the same sentence as ISOC1 in open-access papers:
ISOC1 is named in the same sentence as 18 diseases in open-access papers, as found by Europe PMC text mining. Sharing a sentence is not in itself a finding about the gene and the disease. The quoted sentences say what the papers report.
pancreatic cancer (4 papers, 2022 to 2025). "ISOC1 has been reported to be highly expressed in lung cancer, gastric cancer, colon cancer and pancreatic cancer and also promotes the cancer process and growth of cancer cells." (PMID 35943670, 2023). "Since it has been reported that ISOC1 knock-down suppresses cell proliferation in pancreatic cancer and colon cancer cells, we studied the effect of ISOC1 deletion on cell proliferation in RAW 264.7 cells treated with LPS." (PMID 36144632, 2022).
lung carcinoma (3 papers, 2022 to 2025). "Thus, thanks to co-immunoprecipitation combined with mass spectrometry and RNA sequencing of these KO cell lines they showed that ISOC1 exhibited a tumor-promoting function in lung cancer by interacting with DNA damage repair pathways and mediating inflammation-related signaling pathways." (PMID 36497228, 2022).
colon cancer (2 papers, 2022 to 2023). "For example, it has been reported that knockout of ISOC1 activates the AKT1/GSK-3β pathway and induces the apoptosis of colon cancer cells." (PMID 36144632, 2022).
gastric cancer (2 papers, 2023). A primary or metastatic malignant neoplasm involving the stomach. "Isochorismatase domain-containing 1 (ISOC1) is upregulated in gastric cancer, where it functions to activate and upregulate CDK19 in order to induce proliferation of gastric cancer cells and increase tumor size." (PMID 36769170, 2023).
chronic renal failure (1 paper, 2009). "Several studies have reported the involvement of Isoc1 in progressive chronic renal failure in rats." (PMID 19781091, 2009).
clear cell renal cell carcinoma (1 paper, 2025). "Subsequently, pan-cancer analysis further confirmed that ISOC1 acted as a protective factor for clear cell renal cell carcinoma." (PMID 41210684, 2025). "RT-qPCR analysis revealed that ISOC1 expression was notably higher in HK-2 cells compared to the two clear cell renal cell carcinoma cell lines." (PMID 41210684, 2025).
migraine (1 paper, 2024). "However, the associations between SERPING1 and BRH (PP.H4.abf = 0.47), ARHGAP25 and VD (PP.H4.abf = 0.34), PLG and any migraine (PP.H4.abf = 0.30), as well as ISOC1 and VD (PP.H4.abf = 0.06), did not receive sufficient support from co‐localization analysis, with a PP.H4.abf value below 0.5." (PMID 38898596, 2024).
renal carcinoma (1 paper, 2025). A carcinoma arising from the epithelium of the renal parenchyma or the renal pelvis. "We also analyzed the association between ISOC1 expression levels and the sensitivity to common targeted therapies and immunotherapies in renal cancer cohorts." (PMID 41210684, 2025). "Nevertheless, our findings demonstrate a robust causal association between the protein levels of ISOC1 and the development of renal cancer." (PMID 41210684, 2025). "The analysis revealed that renal cancer patients with elevated ISOC1 expression demonstrated enhanced sensitivity to Sorafenib, Afuresertib, Dabrafenib, Nilotinib and Sabutoclax." (PMID 41210684, 2025). "Subsequently, by integrating eQTL and pQTL Mendelian randomization analyses, we uncovered a robust genetic association between isochorismatase domain-containing protein 1(ISOC1) and renal cancer." (PMID 41210684, 2025). "In order to further elucidate the role of ISOC1 in renal cancer, we undertook a series of in vitro experiments to explore its involvement in the progression and metastasis of RCC." (PMID 41210684, 2025). "In contrast, in the renal cancer cohort with high ISOC1 expression, Macrophages M1, Monocytes and Eosinophils appeared to be more activated." (PMID 41210684, 2025). "This suggested a negative causal relationship between ISOC1 protein levels and renal cancer, aligning with our previous conclusions." (PMID 41210684, 2025). "In both ISOC1 knockdown RCC cell lines, we observed a significant increase in both the number of cell colonies and the percentage of EdU-positive cells compared to the control group, indicating that ISOC1 downregulation enhances the proliferative capacity of renal cancer cells." (PMID 41210684, 2025).
renal cell carcinoma (1 paper, 2025). "Among the genes identified as significantly associated with renal cell carcinoma through eQTL MR analysis, ISOC1 was the only gene that also demonstrated a strong causal association at the protein level, as revealed by pQTL MR analysis." (PMID 41210684, 2025). "Notably, research on ISOC1 in renal cell carcinoma is currently lacking, leaving its role in this malignancy an open question for future investigation." (PMID 41210684, 2025).
tumor (5 papers, 2023 to 2025). "For instance, changes in ISOC1 levels have been linked to shifts in cellular energy metabolism, thereby facilitating tumor growth and progression." (PMID 41210684, 2025). "ISOC1 expression was significantly linked to tumor immune infiltration, drug sensitivity, and patient prognosis." (PMID 41210684, 2025). "Through integrative MR analysis, we identified ISOC1 as a novel RCC-associated gene, with potential tumor-suppressive functions in this specific context." (PMID 41210684, 2025). "ISOC-1 overexpression in NSCLC cells induced cell proliferation, viability, migration, and invasion, whereas ISOC1 knockout in mouse xenograft model led to significant tumor growth inhibition." (PMID 36986550, 2023). "Many studies have shown that ISOC1 was positively correlated in tumor progression." (PMID 35943670, 2023). "In conclusion, this study established ISOC1 as a key regulator in the pathogenesis and progression of RCC, illuminating its critical role in tumor biology." (PMID 41210684, 2025).
cancer (3 papers, 2023 to 2025). A tumor composed of atypical neoplastic, often pleomorphic cells that invade other tissues. "Initial findings indicate that dysregulated ISOC1 expression may contribute to cancer-associated metabolic reprogramming, influencing cell proliferation and survival through alterations in metabolic pathways." (PMID 41210684, 2025). "This integrative approach not only strengthened the validity of ISOC1 as a candidate gene, but also reflected the value of leveraging multi-omics MR strategies to uncover key regulators in cancer biology." (PMID 41210684, 2025). "Isochorismatase domain containing 1 (ISOC1) is a potential biomarker in gastrointestinal cancer, but its role in cancer remains unknown." (PMID 36986550, 2023).
hematological tumors (1 paper, 2025). "Our findings indicate that certain plasma proteins exhibit causative roles in various hematological tumors, specifically ISOC1 in 14 tumors, ADK in 11 tumors, FKBPL in 10 tumors, and BCL2 in 9 tumors." (PMID 41048997, 2025). "For example, ISOC1 is causally associated with 14 hematological tumors." (PMID 41048997, 2025).
infection (1 paper, 2022). The state of being infected such as from the introduction of a foreign agent such as serum, vaccine, antigenic substance or organism. "From the results, we observed that after LPS infection, ISOC1 deletion increased expressions of M1 markers, while it reduced expressions of M2 markers." (PMID 36144632, 2022). "As essential metabolic organelles, peroxisomes have recently been identified as a pivotal regulators of inflammation during infection; we thus tested the peroxisome levels in WT and Isoc1-/- treated with LPS." (PMID 36144632, 2022).
neurological disease (1 paper, 2016). "Interestingly, three hub genes (ENO3, ISOC1 and GNB3) in this cluster were enriched in the first annotation (hereditary disorder) and/or the second annotation (neurological disease) of diseases and functions." (PMID 27462267, 2016).
ISOC1 also shares sentences with these, for which no sentence is quoted: colorectal cancer (1 paper); hepatocellular carcinoma (1); ovarian carcinoma (1); Sepsis (1).